CTBP2 (C-terminal binding protein 2)
Description:
Corepressor targeting diverse transcription regulators. Functions in brown adipose tissue (BAT) differentiation (By similarity). Isoform 2 probably acts as a scaffold for specialized synapses.
Synonyms: ribeye
Tractability: Small molecule: a structure with a bound ligand is known; a high-quality ligand is known; it has a high-quality binding pocket. PROTAC: ubiquitination databases record sites on it; its protein half-life has been measured; a small molecule that binds it is known.
Gene: Protein-coding gene on chromosome 10 (124,981,657 to 125,163,006, reverse strand). Ensembl gene ENSG00000175029.
Subcellular location: Nucleus; Synapse
Subcellular location (Human Protein Atlas): Nucleoplasm
Pathways (Reactome):
Cell-Cell communication: Negative Regulation of CDH1 Gene Transcription
Disease: Signaling by TCF7L2 mutants
Sensory Perception: Sensory processing of sound by inner hair cells of the cochlea
Signal Transduction: Repression of WNT target genes
Gene Ontology:
Molecular function: protein binding; protein kinase binding; protein-containing complex binding; transcription corepressor binding; DNA-binding transcription factor binding; transcription coactivator activity; transcription coregulator binding; transcription corepressor activity; NAD binding; oxidoreductase activity, acting on the CH-OH group of donors, NAD or NADP as acceptor
Biological process: positive regulation of retinoic acid receptor signaling pathway; positive regulation of transcription by RNA polymerase II; negative regulation of cell population proliferation; negative regulation of DNA-templated transcription; negative regulation of transcription by RNA polymerase II; regulation of transcription by RNA polymerase II; viral genome replication; white fat cell differentiation
Cellular component: nucleus; nucleoplasm; transcription repressor complex; synapse
Genetic constraint (gnomAD): Loss-of-function variants: 29 observed, 75.69 expected, observed/expected ratio (o/e) 0.38, 90% interval 0.28 to 0.52. The upper end of that interval is the gene's LOEUF score, 0.52, which puts it in group 2 of 6, group 1 being the genes least tolerant of losing a copy. Missense variants: 1,210 observed, 1,382 expected, observed/expected ratio (o/e) 0.88, 90% interval 0.83 to 0.92. Synonymous variants: 593 observed, 591.18 expected, observed/expected ratio (o/e) 1, 90% interval 0.94 to 1.07.
Homologues: Orthologues: macaque CTBP2 (97% identical), dog CTBP2 (96% identical), guinea pig Ctbp2 (96% identical), mouse Ctbp2 (96% identical), rat Ctbp2 (96% identical), zebrafish ctbp2a (84% identical), tropical clawed frog ctbp2 (77% identical), Drosophila melanogaster CtBP (64% identical), Caenorhabditis elegans ctbp-1 (50% identical), Drosophila melanogaster CG1236 (20% identical), Drosophila melanogaster CG31674 (20% identical), Drosophila melanogaster CG9331 (18% identical), and 1 more. Paralogues in human: CTBP1 (78% identical), PHGDH (26% identical), GRHPR (20% identical).
Diseases named in the same sentence as CTBP2 in open-access papers:
CTBP2 is named in the same sentence as 79 diseases in open-access papers, as found by Europe PMC text mining. Sharing a sentence is not in itself a finding about the gene and the disease. The quoted sentences say what the papers report.
ovarian carcinoma (19 papers, 2013 to 2024). A malignant neoplasm originating from the surface ovarian epithelium. "Hence, both immunofluorescence and co-immunoprecipitation assays suggest that Pinin physically associates with both CtBP1 and CtBP2 proteins in the nuclei of ovarian cancer cells." (PMID 26871283, 2016). "Second, CtBP2 is overexpressed in cancer, including prostate cancer, ovarian cancer, liver cancer, breast cancer, and esophageal squamous cell carcinoma." (PMID 37163116, 2023). "It is reported that MDSCs suppress CtBP2 in ovarian cancer cells by inducing miR-101 expression which enhanced cancer cell stemness and spreading potential." (PMID 36329699, 2022). "It will be an exciting new research direction for CtBP2 role in ovarian cancer, with greater potential translational application for ovarian cancer patients." (PMID 34253710, 2021). "Aberrant expression of CtBP2 has been observed in ovarian cancer, melanoma, breast cancer, and esophageal squamous cell carcinoma." (PMID 34738870, 2021). "According to previously findings, overexpression of CtBP2 was linked with abnormal proliferation, epigenetically silencing BRCA1 function, and poorer survival rate in ovarian cancer patients." (PMID 34253710, 2021). "Recent studies have shown that C-terminal binding protein-1 and -2 (CtBP1/2) are overexpressed in ovarian cancer, and CtBP2 expression is correlated with poor prognosis." (PMID 32332713, 2020). "C-terminal binding protein 2 (CtBP2) is elevated in epithelial ovarian cancer, especially in the aggressive and highly lethal subtype, high-grade serous ovarian cancer (HGSOC)." (PMID 32332713, 2020). "pointed out that CTBP2 is overexpressed in ovarian cancer cells and that CTBP2 can downregulate the target gene of the Wnt signaling pathway and promote the carcinogenesis of ovarian epithelium, but its role in cervical cancer needs further study." (PMID 32993576, 2020). "Based on the prior demonstration of CtBP1/2 overexpression in ovarian cancer, and poor prognosis related to CtBP2 expression, we investigated the cellular CtBP dependency of HGSOC." (PMID 32332713, 2020). "For example, myeloid-derived suppressor cells (MDSC) triggered miR-101 in cancer cells and subsequently repressed CtBP2, leading to the ovarian cancer cell stemness." (PMID 30989585, 2019). "They demonstrated that MDSCs triggered miRNA-101 expression in ovarian cancer cells, and miRNA-101 subsequently repressed the corepressor gene C-terminal binding protein-2 (CtBP2), resulting in enhanced cancer cell stemness." (PMID 30555631, 2018). "CtBP2 is overexpressed in prostate cancer, hepatocellular carcinoma, and ovarian cancer with important effects on the biological activity and prognosis." (PMID 28404932, 2017). "Fluorescence microscopy of ovarian cancer cells stained with fluorescently labeled Pinin and CtBP2 antibodies showed that they were co-localized in the nuclei of the cells, similar to the co-localization of CtBP1 with Pinin (data not shown)." (PMID 26871283, 2016). "Our characterization also indicates that Pinin interacts with both human CtBP1 and CtBP2 proteins in the nuclei of ovarian cancer cells." (PMID 26871283, 2016). "We compared the expression of Pinin, CtBP1, and CtBP2 in these three knockdown cell lines with the control SKOV3-IPLuc cancer cell line, and a pair of SKOV3-IPLuc ovarian cancer cell lines with knockdown of CtBP1 and CtBP2 expression, respectively." (PMID 26871283, 2016). "miR-101 subsequently decreases the corepressor gene C-terminal binding protein-2 (CtBP2), which results in increased cancer cell stemness in ovarian cancer." (PMID 26078490, 2015). "Immunohistochemistry and gene knockdown studies showed OV expression of PKP3 and repression of apoptosis through silencing of death receptors (DRs) 4/5 by C-terminal-binding protein 2 in ovarian cancer cell lines, suggesting a role of these two proteins in the disease's progression." (PMID 39309198, 2024).
ovarian carcinoma (continued). "Indeed, overexpression of CtBP2 has been found in multiple cancers, including ovarian cancer, breast cancer, and hepatocellular carcinoma." (PMID 28404932, 2017). "Whole transcriptomic comparison of next-generation RNA sequencing data between control ovarian cancer cell lines and cancer cell lines with respective knockdown of Pinin, CtBP1, and CtBP2 expression also showed reduced expression of CtBP1 mRNA in the Pinin knockdown cell lines." (PMID 26871283, 2016). "As we previously have shown that CtBP2 is overexpressed in ovarian cancer, it would be of interest to investigate whether CtBP2 also interacts with Pinin." (PMID 26871283, 2016). "A very recent study reported an elevation of CtBP2 in ovarian cancer and suggested that CtBP2 expression could be used as a marker for patients that are more likely to respond to epigenetic therapy utilizing histone deacetylase inhibitors." (PMID 23762064, 2013). "In support of our conclusion that CtBP represses the drug resistance of ovarian cancer cells, the pair-wise comparison between cisplatin-resistant and cisplatin-sensitive A2780 cancer cells disclosed that cisplatin-resistant cells significantly downregulated both CtBP1 and CtBP2." (PMID 37151877, 2023). "A recent report also showed that increased miR-101 levels are negatively associated with the overall survival (OS) and disease-free interval (DFI) in patients with ovarian carcinoma and miR-101 could target C-terminal binding protein-2 (CtBP2) to enhance the stemness of cancer cells." (PMID 26841847, 2016).
prostate carcinoma (16 papers, 2010 to 2024). A carcinoma that arises from epithelial cells of the prostate gland. "By using microarray data, we observed a potential association between CTBP2 and the regulation of expression levels of these genes in prostate cancer cells." (PMID 38698344, 2024). "We also identified a potential association between CTBP2 the prognosis of prostate cancer, as well as its potential influence on TILs." (PMID 38698344, 2024). "For prostate cancer-associated rs7077275, the risk allele enhances CTCF binding and enhances the allele-specific expression of CTBP2, which decreases the apoptosis of prostate cancer cells and increases tumor growth in a mouse xenograft model of human prostate cancer." (PMID 33919522, 2021). "Lower expression of CTBP2 was associated with poor recurrence-free survival in prostate cancer." (PMID 31323811, 2019). "A joint GWAS showed that CTBP2 for SNP rs4962416 was significantly associated with prostate cancer." (PMID 31323811, 2019). "Further, CTBP2 is overexpressed in prostate cancer and associated with tumor progression." (PMID 30709419, 2019). "However, our analysis of TCGA data showed that high expression of CTBP2 was associated with longer RFS in prostate cancer patients." (PMID 31323811, 2019). "Our previous experiments showed that knockdown of CTBP2 in prostate cancer cell lines affects their proliferation and migration abilities." (PMID 38698344, 2024). "Then, we employed TISIDB (an integrated repository portal for tumor-immune system interactions) to investigate the relationship between CTBP2 expression and the infiltration of immune cells in prostate cancer." (PMID 38698344, 2024). "In this study, we identified CTBP2 as a candidate AR/OCT1 target gene and showed that it is associated with prognosis of prostate cancer." (PMID 38698344, 2024). "CTBP expression is upregulated in malignant tissues, and CTBP2 is highly expressed in prostate cancer, breast cancer, esophageal cancer, liver cancer, and other common tumors." (PMID 37563730, 2023). "Silencing of CTBP2 markedly increases apoptosis of prostate cancer cells; decreases the expression of IL-8, AT2R, CCND1, MMP9, MYC, and HSPC111; and reduces tumor growth in mouse xenograft model of human prostate cancer." (PMID 31323811, 2019). "CTBP2 is overexpressed in prostate cancer, and its increased expression is significantly correlated with malignant behaviors." (PMID 31323811, 2019). "We also noted differences in the total expression of the SLC22A3 and CTBP2 genes in BPH compared with prostate cancer." (PMID 20569440, 2010). "Collectively, these findings suggest that CTBP2 may exert an overall immunosuppressive effect, thereby favoring tumor growth in the prostate cancer microenvironment." (PMID 38698344, 2024). "High CTBP2 expression levels correlate with poor prognosis in prostate cancer patients, while CTBP2 suppresses cancer-inhibiting genes and AR inhibitory factors, such as NCOR and RIP140, by binding to their transcription regulatory regions in prostate cancer cells." (PMID 38698344, 2024). "Additionally, CTBP2 is related to angiogenesis in prostate cancer cells, and silencing CTBP2 can promote prostate cancer cell apoptosis." (PMID 32993576, 2020). "CtBP2 was originally investigated in the context of prostate cancer, and recent reports indicate that CtBP2 can modulate androgen receptor activity to promote prostate cancer progression." (PMID 28404932, 2017). "Furthermore, TISIDB analysis suggested the relationship between CTBP2 expression and immune cell infiltration in prostate cancer, suggesting that it may contribute to immune evasion in CRPC." (PMID 38698344, 2024). "The c-terminal binding protein-2 (CTBP2) is a highly conserved transcriptional co-repressor that has been reported to be involved in the development and progression of several human cancers and associated with the poor prognosis of prostate cancer and lung cancer." (PMID 35113002, 2022).
prostate carcinoma (continued). "CTBP2, as an oncogene which can inhibit E-ca gene expression, is frequently reported to promote the cell proliferation, migration, invasion and drug resistance in a variety of cancers such as breast cancer, prostate cancer, esophageal cancer and colorectal cancer." (PMID 34781990, 2021). "CTBP2 expression was significantly elevated in metastatic CRPC tissues compared to that in benign and primary prostate cancer tissues." (PMID 38698344, 2024). "In the human neuroblastoma cell line SHSY5Y and prostate cancer PC3 cells, the downregulation of CtBP2 inhibited cell proliferation and arrested the cell cycle, by decreasing the expression of c-Myc." (PMID 33490060, 2020). "CTBP2 and SLC22A3 mRNA levels were reduced by 27% and 50% in prostate cancer tissues compared with BPH tissues (4.2 [IQR 2.5] v/s 2.1[IQR 1.6]; P = 0.008 for CTBP2 and 0.48 [IQR 0.75] v/s 1.01 [IQR 1.42]; P = 0.015 for SLC22A3)." (PMID 20569440, 2010). "Using the Cancer Genome Atlas (TCGA) dataset, we observed that high expression of CTBP2 was significantly correlated with poor overall survival of prostate cancer patients, while AKAP12, HIF1A and RHOB were not." (PMID 38698344, 2024). "In the present study, we observed a negative correlation between CTBP2 expression in prostate cancer and MDSCs and TAMs, which are known to promote tumor progression." (PMID 38698344, 2024). "When compared to normal prostate tissues (N = 52), the CTBP2 expression level was significantly higher in prostate cancer tissues (N = 498) (p = 0.0185), while the NCOA4 expression was significantly lower in prostate cancer tissues (p = 0.0131)." (PMID 31323811, 2019).
breast carcinoma (15 papers, 2016 to 2024). "Recently, CTBP2 has been linked to the inhibition of cholesterol synthesis in breast cancer cells through direct repression of SREBF2 expression." (PMID 36414381, 2023). "In the present study, we investigated the detailed mechanisms by which CtBP2 contributes to the development of breast cancer and the predictive value of CtBP2 and associated pathways in the prognosis of breast cancer." (PMID 28412731, 2017). "According to this possibility, CTBP2 repression of fatty acid in breast cancer requires the interaction with the transcriptional repressor ZEB1, which was never detected as a CTBP2 partner in our co-immunoprecipitation analysis in GBM cells." (PMID 36414381, 2023). "The deregulation of CtBP2 target genes in breast cancer samples with respect to normal tissues was also confirmed by analyzing another TCGA-independent datasets available from the GEO public repository at the accession number GSE37751." (PMID 34680207, 2021). "RNA-sequencing data retrieved from TCGA for 103 invasive breast adenocarcinomas and 103 matched normal samples showed that CtBP2 expression is higher in breast cancer than in normal tissues, consistent with previous data." (PMID 34680207, 2021). "Hierarchical clustering of CtBP2 target genes highlighted a distinctive transcriptomic profiling of breast cancer samples compared to normal tissues." (PMID 34680207, 2021). "Further, we demonstrated that co-expression of Zeb1 and CTBP2 in breast cancer patients correlated with the poor survival prognosis, thus signifying the functionality of the Zeb1–CTBP2 interaction." (PMID 34074001, 2021). "Using this available data, 126 breast cancer patients were quantitively stratified according to CtBP1, CtBP2, and LSD1 nuclear expression into low, medium and high terciles of expression." (PMID 31534138, 2019). "Collectively, these findings provide insight into the role CtBP2 plays in promoting proliferation and migration in breast cancer by the inhibition of p16INK4A." (PMID 28412731, 2017). "We observed that the track length of EGFP-CtBP2 breast cancer cells migrating into the cell free areas was significantly longer than those of CtBP2-shRNA cells." (PMID 28412731, 2017). "Functional assays, including colony formation, wound healing, transwell invasion, anchorage-independent growth assay and a xenograft tumor model were used to determine the oncogenic role of CtBP2 in breast cancer progression." (PMID 28412731, 2017). "Western blot and immunochemistry were employed to evaluate the level of CtBP2 and p16INK4A in breast cancer." (PMID 28412731, 2017). "In agreement with previous studies, the present study also found that CtBP2 enhances migration in breast cancer." (PMID 28412731, 2017). "IHC analysis revealed that the expression of CtBP2 in breast cancer samples was positively correlated with breast cancer malignancy." (PMID 28412731, 2017). "The expression of p16INK4A was strong; however, CtBP2 was strongly expressed in tissues from breast cancer samples and four breast cancer cell lines." (PMID 28412731, 2017). "The Cox's proportional hazards regression model demonstrated that expression level of CtBP2 and p16INK4A, histological grade, tumor size and metastases were independently predictive factors for an adverse prognosis in patients with breast cancer." (PMID 28412731, 2017). "The expression of CtBP2 was detected during the progression of the cell cycle in breast cancer cells." (PMID 28412731, 2017). "Our in vitro studies indicated that functional overexpression of CtBP2 makes breast cancer cells phenotypically more malignant, and underexpression of CtBP2 makes the same cells less malignant." (PMID 28412731, 2017). "Immunohistochemical staining was used to determine the physiological and pathological interaction between CtBP2, p16INK4A and the proliferation index Ki-67 in tissue samples from patients with both benign breast disease and breast cancer." (PMID 28412731, 2017).